GPR37 (G protein-coupled receptor 37)
Diseases named in the same sentence as GPR37 in open-access papers (continued):
Sharing a sentence is not in itself a finding about the gene and the disease.
colorectal cancer (6 papers, 2023 to 2025). A primary or metastatic malignant neoplasm that affects the colon or rectum. "In the context of colorectal cancer (CRC), the G Protein-Coupled Receptor 37 (GPR37) receptor enhances the expression of lactate dehydrogenase A (LDHA) and increases glycolytic activity by activating the Hippo signaling pathway." (PMID 40342932, 2025). "For example, G protein-coupled receptor 37 (GPR37) enhances glycolysis and histone lactylation through the Hippo pathway, promoting the liver metastasis of colorectal cancer." (PMID 40057816, 2025). "Previous studies have shown that GPR37 can interact with CDK6, influence the tumor progression of lung adenocarcinoma, and promote metastasis in colorectal cancer through the Hippo pathway." (PMID 39730361, 2024).
lung adenocarcinoma (6 papers, 2021 to 2024). A carcinoma that arises from the lung and is characterized by the presence of malignant glandular epithelial cells. "The down-regulation of GPR37 expression can significantly inhibit the proliferation and migration of lung adenocarcinoma in vitro and in vivo." (PMID 36339610, 2022). "The expression of the 6 key genes (FKBP3, GPI, LOXL2, IL22RA1, GPR37, has-miR-148a-3p) in lung adenocarcinoma patients with different tumor stages, T stages, N stages and M stages." (PMID 34040139, 2021). "GPR37 belongs to the G protein-coupled receptor family, and GPR37 can induce lung adenocarcinoma cell cycle arrest in G1 phase by binding to CDK6, thereby enhancing the progression and migration of lung adenocarcinoma cells." (PMID 36712848, 2022).
Stroke (6 papers, 2020 to 2025). Sudden impairment of blood flow to a part of the brain due to occlusion or rupture of an artery to the brain. "In post-stroke brain tissue, GPR37 deficiency leads to downregulation of phosphorylated mTOR and its downstream effectors S6 kinase and 4E-BP1, particularly in regions enriched for NPCs." (PMID 40822851, 2025). "Functionally, loss-of-function studies have demonstrated that GPR37 facilitates neural progenitor cell survival, proliferation, and migration following stroke." (PMID 40822851, 2025). "GPR37 is expressed by neurons and oligodendrocytes in the brain and has been implicated in multiple disorders, such as demyelination, Parkinson’s disease, stroke, and cancer." (PMID 36430912, 2022). "GPR37 has been implicated in several neurological disorders, such as PD and stroke, and in cancer." (PMID 36430912, 2022). "In animal models of cerebral ischemia, GPR37 expression is upregulated in the penumbral cortex and hippocampus within 48–72 h after stroke onset, with predominant localization in neuronal populations and neural progenitor cells (NPCs)." (PMID 40822851, 2025). "Ten days following stroke, Gpr37-/- mice exhibited significantly reduced glial scar formation, potentially implying an enhanced regenerative response in these mice." (PMID 35409385, 2022). "Following stroke injury, GPR37 is increased within a population of Sox2-positive progenitor cells and acts as a negative regulator of progenitor cell dynamics and gliosis following ischemic injury." (PMID 36430912, 2022). "Future studies are needed to fully understand the role of GPR37 in modulating both inhibitory and excitatory signals which regulate excitotoxity following stroke." (PMID 35409385, 2022). "Given the potential role for inhibitory GABAergic interneurons in modulating the brain’s plasticity and repair following stroke, the ability of GPR37 to modulate this response would be an intriguing direction for further investigation." (PMID 35409385, 2022). "Future studies are needed to assess the contribution of macrophage-expressed GPR37 in resolving inflammation and repair following stroke." (PMID 35409385, 2022). "A protective role of GPR37 is further supported by stroke models where GPR37KO animals showed exacerbated inflammatory process after injury." (PMID 32292338, 2020). "In a stroke model, GPR37 negatively correlates with serum inflammatory factor levels." (PMID 39633709, 2024). "In addition, GPR37 levels are significantly negatively correlated with the NIH Stroke Scale (NIHSS) scores." (PMID 39633709, 2024). "A recent study highlighting the role of GPR37 in mediating glial cell responses following stroke examined prosaposin levels within the peri-infarct region of wild-type and GPR37 knock-out (Gpr37-/-) mice and did not observe detectable differences in prosaposin expression." (PMID 35409385, 2022). "Lower serum GPR37 levels and higher levels of inflammatory markers such as S100β, neuron-specific enolase (NSE), IL-1β, and TNF-α are observed in stroke patients compared to healthy controls." (PMID 39633709, 2024). "Therefore, targeting GPR37 may offer great drug discovery opportunities for treating demyelinating diseases such as multiple sclerosis, as well as neurological diseases such as traumatic brain injury and stroke." (PMID 36430912, 2022).
hepatocellular carcinoma (5 papers, 2018 to 2023). A malignant tumor that arises from hepatocytes. "Conversely, GPR37 was poorly expressed in multiple myeloma cell adhesion model and hepatocellular carcinoma." (PMID 33364431, 2021). "Transient knockdown of GPR37 by siRNA in HuH7 cells significantly reduced apoptosis in hepatoma cells, with activation of the 3-Akt phosphatidylinositol signaling pathway." (PMID 33810360, 2021). "Furthermore, the transient GPR37 knockdown by siRNA in HuH7 cells strikingly decreases the apoptosis of hepatoma cells and increases cell proliferation by activating the PI3K-Akt signaling pathway." (PMID 29734668, 2018). "In hepatocellular carcinoma, patients with low GPR37 expression had a shorter survival time, which may be due to the inhibition of proliferation of HCC cells caused by downregulation of GPR37." (PMID 33364431, 2021). "Immunohistochemistry and Western blot analyses in hepatocellular carcinoma samples revealed low expression of GPR37 in hepatocellular carcinoma (HCC) as compared to non-tumorous tissues nearby." (PMID 36430912, 2022).
ischemic stroke (5 papers, 2020 to 2025). A stroke disorder caused by obstruction of blood flow to the brain, due to thrombotic (local blood clot formation) or embolic (due to a blood clot or other material traveling from another site) event. "The focus of this review will thus be on the emerging roles of two brain-expressed orphan GPCRs, GPR37 and GPR37 L1, in regulating various cellular and molecular processes underlying ischemic stroke." (PMID 35409385, 2022). "Demonstration of the protective effect of GPR37 by modulating inflammatory and multicellular death pathways after ischemic stroke in mice." (PMID 40822851, 2025). "Cellular communication via direct and paracrine mechanisms thus adds an additional layer of complexity to disentangling the precise contribution of GPR37 and GPR37 L1 signaling in ischemic stroke." (PMID 35409385, 2022). "After ischemic stroke, the down-regulation of GPR37 can induce autophagy via inhibiting the mTOR signaling pathway." (PMID 35109896, 2022). "The focus of this review will thus be on the roles of two brain expressed orphan GPCRs, namely GPR37 and GPR37L1, in regulating various pathological processes underlying ischemic stroke." (PMID 35409385, 2022). "Interestingly, GPR37 has been found to be intricately involved in mediating astrogliosis following ischemic stroke." (PMID 35409385, 2022). "Based on the fact that Gpr37 (-/-) mice exhibited increased apoptosis and infarct size, it has recently been suggested that GPR37 is also involved in cell damage protection and inflammation after ischemic stroke." (PMID 33321955, 2020). "However, other studies with Gpr37 and Gpr37l1 null mutant models of seizure susceptibility, ischemic stroke, and central cardiovascular control have not confirmed the co-expression of prosaposin and the two putative receptors, or the prosaptide-mediated activation of their intracellular signaling." (PMID 35457105, 2022).
Alzheimer disease (4 papers, 2017 to 2022). A progressive, neurodegenerative disease characterized by loss of function and death of nerve cells in several areas of the brain leading to loss of cognitive function such as memory and language. "An engineered in-house nanoluciferase-based immunoassay was used to quantify ecto-GPR37 in CSF samples from neurological control (NC) subjects, PD patients and Alzheimer’s disease (AD) patients." (PMID 33637132, 2021). "Based on our results, the suspected beneficial effect of 5‐HT4d on Alzheimer disease development is expected to be amplified in cells co‐expressing either GPRIN2 or GPR37." (PMID 28298427, 2017). "First, we found that GPRIN2 and GPR37 physically and functionally interact with the 5‐HT4d receptor, a promising target for Alzheimer's disease." (PMID 28298427, 2017). "Furthermore, the ecto-GPR37 peptides are significantly increased in the cerebrospinal fluid (CSF) of PD patients but not increased in the CSF of Alzheimer’s disease patients, suggesting that ecto-GPR37 may serve as a potential biomarker for PD." (PMID 36430912, 2022).
glioma (4 papers, 2023 to 2025). A benign or malignant brain and spinal cord tumor that arises from glial cells (astrocytes, oligodendrocytes, ependymal cells). "Consistent with this, overexpression of GPR37 was linked to poor prognosis in glioma patients in terms of the likelihood of overall survival (OS) (P < 0.001)." (PMID 37837549, 2023). "Through bioinformatics analysis, we found that GPR37 was noticeably up-regulated in glioma tissues, and associated with poor prognosis." (PMID 37837549, 2023). "Finally, hypomethylation of the GPR37 promoter was associated with its high expression levels and poor prognosis in glioma." (PMID 37837549, 2023). "The convergence of these two functional domains–tumor proliferation and immune suppression–underscores GPR37’s multifaceted contribution to glioma biology." (PMID 40822851, 2025). "Overexpression of GPR37 in U251 glioma cells promotes proliferation, migration, and colony formation, while silencing GPR37 via siRNA attenuates these tumorigenic behaviors." (PMID 40822851, 2025). "In sum, GPR37 integrates oncogenic signaling and immune landscape modulation in gliomas, positioning it as a promising–but complex–therapeutic target in malignant brain tumors." (PMID 40822851, 2025). "Knockdown of GPR37 leads to p-Akt reduction, G1 phase arrest, and upregulation of the cyclin-dependent kinase inhibitor p21, linking GPR37 to oncogenic signaling and cell cycle progression in glioma cells." (PMID 40822851, 2025). "At the cellular level, GPR37 is upregulated in high-grade gliomas compared to adjacent normal tissues, as shown by transcriptomic and immunohistochemical analyses." (PMID 40822851, 2025). "Its ability to activate downstream neurogenic or proliferative programs positions HA as a molecular probe for studying GPR37 signaling in neural stem cells and glioma models." (PMID 40822851, 2025). "In glioma cell lines, transient knockdown of GPR37 using specific siRNA leads to reduced Akt phosphorylation and a concomitant increase in cell cycle inhibitors such as p21, resulting in G1 phase arrest." (PMID 40822851, 2025). "Research indicates that GPR37 is highly expressed in gliomas, where it plays a crucial role in promoting tumor cell proliferation and migration." (PMID 39633709, 2024). "For instance, in glioma, elevated GPR37 is positively correlated with increased infiltration of M2 macrophages, which is associated with a poor prognosis." (PMID 39633709, 2024). "The possible biological mechanisms of GPR37 provide novel insights into the clinical diagnosis and treatment of glioma." (PMID 37837549, 2023). "Since DNA methylation is a critical epigenetic modification that is associated with tumor progression, we also screened for the methylated sites in GPR37 and analyzed the correlation between GPR37 methylation and expression in glioma." (PMID 37837549, 2023). "We further analyzed the data from TCGA databases to explore a possible link between GPR37 and clinicopathological characteristics of glioma patients." (PMID 37837549, 2023). "Up-regulation of GPR37 in the U251 glioma cell line accelerated cell cycle progression, activate AKT pathway and promote proliferation." (PMID 37837549, 2023). "To explore the role played by GPR37 in the development and progression of glioma, we screened for the co-expressed genes using the LinkedOmics database." (PMID 37837549, 2023). "With normal tissues adjacent to the tumor as the control group, the GPR37 expression in different grade of glioma were statistically analyzed in 38 samples." (PMID 37837549, 2023). "To that end, we investigated the prognostic significance and putative biological functions of GPR37 in glioma using bioinformatics." (PMID 37837549, 2023). "Beyond tumor cell-autonomous functions, GPR37 also influences the glioma immune microenvironment." (PMID 40822851, 2025). "In cultured human glioma U251 cells, GPR37 expression is significantly upregulated after 2 days." (PMID 39633709, 2024).
glioma (continued). "In summary, GPR37 may increase the incidence and development of glioma by regulating the PPAR pathway, which requires more investigation." (PMID 37837549, 2023). "Therefore, we also analyzed the correlation between GPR37 expression in glioma and immune infiltration." (PMID 37837549, 2023). "GPR37 is frequently overexpressed in glioma and is an independent prognostic predictor." (PMID 37837549, 2023). "Although the involvement of GPR37 in the growth and prognosis of several malignancies has been partially validated, its role in glioma remains unknown." (PMID 37837549, 2023). "GPR37 mRNA expression and clinicopathological variables of glioma." (PMID 37837549, 2023). "However, there is little conclusive data regarding the involvement of GPR37 in the genesis and progression of glioma." (PMID 37837549, 2023). "GPR37 was significantly up-regulated in glioma compared to normal brain tissues." (PMID 37837549, 2023). "What is more, the overexpression of GPR37 in glioma may be due to DNA hypomethylation." (PMID 37837549, 2023). "Thus, GPR37 maybe contribute to glioma progression by recruiting TAMs and promoting M2 polarization." (PMID 37837549, 2023). "Thus, GPR37 may influence macrophage polarization in glioma." (PMID 37837549, 2023). "Immunohistochemical staining of clinical 38 samples also confirmed that the different level of GPR37 expression in tumor tissues were in CNS WHO grade 2, 3 and 4 of glioma." (PMID 37837549, 2023). "The aim of this study was to explore the relationship between GPR37 gene expression and the clinicopathological factors, patient prognosis, tumor-infiltrating immune cell signature GSEA and methylation levels in glioma." (PMID 37837549, 2023). "In addition, we also identified GPR37 as an independent prognostic factor for both OS and DSS in glioma." (PMID 37837549, 2023).
multiple system atrophy (4 papers, 2015 to 2025). Multiple system atrophy (MSA) is a neurodegenerative disorder characterized by autonomic failure (cardiovascular and/or urinary), parkinsonism, cerebellar impairment and corticospinal signs with a median survival of 6-9 years. "Evidence from reported studies shows that the specific up-regulated DEPs of GPR37 are hypothesized to be the targets of miR-29c-3p in the striatal microRNA-mRNA networks of neuroinflammation in multiple system atrophy." (PMID 38256016, 2024). "In addition, it would be necessary to explore whether the CSF ecto-GPR37 can be used for the differential diagnosis between PD and atypical parkinsonism, including LB dementia, multiple system atrophy, progressive supranuclear palsy and corticobasal syndrome." (PMID 33637132, 2021).
Sepsis (4 papers, 2021 to 2022). Sepsis is defined as life-threatening organ dysfunction caused by a dysregulated host response to infection. "In all three models, we found that host GPR37 confers protection against infection, sepsis, and sepsis-associated adverse events, including serum cytokine production, hypothermia, pain, and death." (PMID 33731716, 2021). "In contrast, adoptive transfer of GPR37-activated macrophages by ARU or NPD1 significantly alleviated sepsis and malaria infection." (PMID 36430912, 2022). "Recent studies showed that GPR37 is expressed in macrophages and plays a protective role via the regulation of inflammation in sepsis, bacterial infection, inflammatory pain, and ischemic stroke." (PMID 35625743, 2022). "In this study, we extend these findings, demonstrating that GPR37 confers protection against sepsis or infection following challenge with LPS, bacterial infection by L.m., or parasite infection by P.b." (PMID 33731716, 2021). "In this study, we explored the role of GPR37 in sepsis using several mouse models, including high dose administration of systemic lipopolysaccharide (LPS, also known as endotoxin), bacterial infection with Listeria monocytogenes (L.m)." (PMID 33731716, 2021). "Although at present no conditional knockout tools exist to confirm these findings, these results strongly suggest that GPR37 in macrophages is sufficient to confer protection against sepsis and/or infection in these models." (PMID 33731716, 2021). "Similar approaches could then be applied to the characterization of the proposed interaction between neuroprotectin D1 and Gpr37 in macrophages and the resulting protective effects against infective sepsis and inflammatory pain." (PMID 35457105, 2022). "GPR37 and macrophages further show protection against sepsis following malaria." (PMID 36430912, 2022). "Given an important role of GPR37 in macrophage phagocytosis and inflammation resolution, GPR37 agonists could be developed to treat sepsis after bacterial and parasite infections." (PMID 36430912, 2022). "Additionally, L.m.-induced septic death and sepsis-associated comorbidities (hypothermia, systemic IL-6 surge) were significantly attenuated by the transfer of NPD1-primed WT pMΦ in both WT and Gpr37−/− mice." (PMID 33731716, 2021). "We first examined whether protectin D1/neuroprotectin-D1 (PD1/NPD1) could regulate sepsis in wild-type (WT) and Gpr37−/− mice following LPS and L.m." (PMID 33731716, 2021). "Together, these data suggest that ARU confers GPR37-dependent protection in different models of sepsis, and thus, may be of therapeutic value beyond the treatment of malaria." (PMID 33731716, 2021). "Taken further, we posit that GPR37 agonists could be developed to treat infection and/or sepsis after bacterial and parasite infections as well as infection-induced pain." (PMID 33731716, 2021). "Here we report a protective role of GPR37 in multiple models of infection and sepsis." (PMID 33731716, 2021). "Our findings reveal physiological actions of ARU in host cells by activating macrophages and suggest that GPR37 agonists may help to treat sepsis, bacterial infections, and malaria." (PMID 33731716, 2021). "Here the authors show that GPR37 can modulate sepsis in several animal models." (PMID 33731716, 2021). "To determine whether macrophages confer the protective effects of NPD1 against sepsis in vivo, we treated peritoneal macrophages (pMφ) from WT and Gpr37-KO mice with NPD1 (30 nM) and measured pro-inflammatory cytokines in response to challenge with vehicle, LPS (1 μM), or L.m." (PMID 33731716, 2021). "However, it remains unknown whether GPR37 also plays a role in regulating protective immunity against pathogens, infection, or sepsis." (PMID 33731716, 2021). "Thus, our study suggests that GPR37 agonists may be a prospective therapeutic strategy to treat sepsis, infections, and malaria." (PMID 33731716, 2021).